ESRP2 (epithelial splicing regulatory protein 2)
Description:
mRNA splicing factor that regulates the formation of epithelial cell-specific isoforms. Specifically regulates the expression of FGFR2-IIIb, an epithelial cell-specific isoform of FGFR2. Also regulates the splicing of CD44, CTNND1, ENAH, 3 transcripts that undergo changes in splicing during the epithelial-to-mesenchymal transition (EMT). Acts by directly binding specific sequences in mRNAs. Binds the GU-rich sequence motifs in the ISE/ISS-3, a cis-element regulatory region present in the mRNA of FGFR2.
Synonyms: RBM35B; FLJ21918
Tractability: PROTAC: ubiquitination databases record sites on it; its protein half-life has been measured.
Gene: Protein-coding gene on chromosome 16 (68,229,033 to 68,238,102, reverse strand). Ensembl gene ENSG00000103067.
Subcellular location: Nucleus
Subcellular location (Human Protein Atlas): Nucleoplasm
Pathways (Reactome):
Signal Transduction: FGFR2 alternative splicing
Gene Ontology:
Molecular function: mRNA binding; protein binding; RNA binding; nucleic acid binding
Biological process: regulation of RNA splicing
Cellular component: nucleoplasm; nucleus; ribonucleoprotein complex
Genetic constraint (gnomAD): Loss-of-function variants: 48 observed, 81.08 expected, observed/expected ratio (o/e) 0.59, 90% interval 0.47 to 0.75. The upper end of that interval is the gene's LOEUF score, 0.75, which puts it in group 3 of 6, group 1 being the genes least tolerant of losing a copy. Missense variants: 863 observed, 989.69 expected, observed/expected ratio (o/e) 0.87, 90% interval 0.82 to 0.92. Synonymous variants: 383 observed, 414.38 expected, observed/expected ratio (o/e) 0.92, 90% interval 0.85 to 1.01.
Homologues: Orthologues: chimpanzee ESRP2 (99% identical), macaque ESRP2 (98% identical), rabbit ESRP2 (95% identical), pig ESRP2 (94% identical), dog ESRP2 (94% identical), mouse Esrp2 (93% identical), rat Esrp2 (92% identical), guinea pig ESRP2 (91% identical), zebrafish esrp2 (61% identical), Drosophila melanogaster fus (43% identical), Caenorhabditis elegans sym-2 (28% identical), Drosophila melanogaster glo (15% identical), and 2 more. Paralogues in human: ESRP1 (57% identical), HNRNPH2 (17% identical), HNRNPH1 (17% identical), GRSF1 (16% identical), HNRNPF (16% identical), RBM12B (15% identical), RBM12 (13% identical), HNRNPH3 (12% identical).
Diseases named in the same sentence as ESRP2 in open-access papers:
ESRP2 is named in the same sentence as 44 diseases in open-access papers, as found by Europe PMC text mining. Sharing a sentence is not in itself a finding about the gene and the disease. The quoted sentences say what the papers report.
breast carcinoma (11 papers, 2017 to 2025). "Intriguingly, He and co-workers showed that epithelial splicing regulatory protein (ESRP2), which is involved in the generation of splice variants, is highly expressed in breast cancer and correlated with poor prognosis in these patients." (PMID 40361385, 2025). "For its particular methylation status, ESRP2 is overexpressed as induced by gene hypo-methylation in ovarian cancer and breast cancer." (PMID 32528944, 2020). "The expression of both ESRP1 and ESRP2 is differentially regulated by cell density and hypoxia in breast cancer cells, suggesting local and microenvironmental control of p120 isoform expression." (PMID 31569498, 2019). "On the basis of these assumptions, we tested two ratios between the epithelial and mesenchymal specific splicing factors, ESRP1/RBFOX2 and ESRP2/RBFOX2 in an early breast cancer setting." (PMID 27911856, 2017). "In addition, overexpression of ESRP1 and ESRP2 in basal-like breast cancer cells resulted in upregulation of E-cadherin expression, while in an ER-negative breast cancer model (MDA-MB-231 cells), low ESRP1 expression was associated with the development of EMT." (PMID 36052258, 2022). "In addition, there are reports of DNA methylation changes in ESRP1 in prostate cancer and of ESRP2 in breast cancer, and our examination of TCGA data demonstrated ESRP2 methylation changes in several other adult cancer types." (PMID 34520622, 2022). "The TF SPI1 and the RBPs ESRP1, ESRP2 and PCBP1 featured frequently in detected statistical interactions, suggesting additional mechanistic roles for these proteins in breast cancer." (PMID 38838009, 2024). "ESRP1 has been reported as controlling ER+ breast cancer, and ESRP1/ESRP2 were noted as being the most strongly down-regulated RBPs in epithelial-to-mesenchymal transition (EMT) in a cell culture model of breast cancer." (PMID 38838009, 2024). "To identify a new early prognostic marker of metastasis, we evaluated EMT-related gene expression in breast cell lines, and in primary tumor tissue from 31 patients with early breast cancer, focusing our attention on EMT-related splicing factors ESRP1, ESRP2 and RBFOX2." (PMID 27911856, 2017). "have experimentally demonstrated that compared to non-breast cancer patients, the mRNA expression level of ESRP1 is significantly upregulated in breast cancer tissue samples, while the mRNA expression level of ESRP2 is not upregulated." (PMID 40046628, 2025). "No peaks were found at the ESRP2 and CDH1 gene loci in MCF7 cells, which likely reflected the low expression of ZEB1 in luminal‐type breast cancer cells." (PMID 28618162, 2017).
prostate carcinoma (6 papers, 2019 to 2024). A carcinoma that arises from epithelial cells of the prostate gland. "High ESRP2 expression associated with lymph node metastasis (p < 0.0001) has been reported in prostate cancer." (PMID 38893126, 2024). "Recent data have identified an important mechanism controlling ESRP1 and ESRP2 expression within prostate cancer cells that is linked to disease progression." (PMID 37752235, 2023). "The fact that nuclear ESRP1 and ESRP2 overexpression were strongly associated with unfavorable prostate cancer phenotype and poor patient outcome is in line with previous studies describing a link of high ESRPs expression and an unfavorable phenotype in breast and ovarian cancer." (PMID 33339518, 2020). "To assess how important ESRP2-regulated mRNAs might be in prostate cancer we monitored associated data for time taken to first biochemical tumour recurrence available in the TCGA PRAD cohort, in which information for 38/44 ESRP-regulated exons was available." (PMID 31478829, 2019). "Global RNAseq studies have identified multiple splicing targets for ESRP1 and ESRP2 in prostate cancer cells." (PMID 37752235, 2023). "Expression levels of ESRP1 and ESRP2 genes also decrease in response to enzalutamide, a drug blocking AR function in prostate cancer cells." (PMID 37752235, 2023). "The splicing patterns of NUMB exon 3, MYO1B exon 23 and other ESRP-target exons can be experimentally modulated either by depleting ESRP1 and ESRP2 protein levels in prostate cancer cells, or by using drugs like Casodex to interfere with AR signalling." (PMID 37752235, 2023). "We suggest that the origin of prostate cancer within epithelial cells, and the subsequent association of ESRP1 and ESRP2 expression with more aggressive disease progression, identify ESRP1 and ESRP2 as lineage survival oncogenes." (PMID 37752235, 2023). "Analysis of ESRP1/ESRP2 protein staining in thousands of prostate tumours show that levels of ESRP1/ESRP2 proteins are highest in prostate cancers that are also positive for the TMPRS22-ERG genetic fusion." (PMID 37752235, 2023). "For example, a splice isoform is produced from the MAP3K7 gene (that encodes a mitogen activated protein kinase enzyme) that skips exon 12 in response to ESRP1/ESRP2 depletion in prostate cancer cells." (PMID 37752235, 2023). "This study was undertaken to estimate the impact of ESRP1 and ESRP2 alterations on prostate cancer patient prognosis." (PMID 33339518, 2020). "Our study identifies high expression of ESRP1 and ESRP2 as strong and statistically independent prognostic markers in prostate cancer." (PMID 33339518, 2020). "This is in line with one meta-analysis describing significant upregulation of ESRP1 and ESRP2 mRNA in 719 analyzed prostate cancers from 11 previous studies compared to normal prostate tissue." (PMID 33339518, 2020). "The ESRP1/ESRP2 score analysis showed a striking combined impact of combined ESRP1 and ESRP2 expression on prostate cancer prognosis." (PMID 33339518, 2020). "Because of their low normal endogenous expression profiles, we selected PC3 and DU145 cells to study the effects on prostate cancer cells of ESRP1/ESRP2 protein up-regulation." (PMID 31478829, 2019). "(D) Western blot analysis of ESRP2 levels in a range of prostate cancer cell lines (actin was used as a loading control)." (PMID 31478829, 2019). "Over-expression of both ESRP1 and ESRP2 (either alone or together) in PC3 cells also significantly slowed growth of prostate cancer xenografts in vivo." (PMID 31478829, 2019). "Amongst the key data supporting this proposed model, we find that ESRP2 is a direct and early target for transcriptional activation by the AR in prostate cancer cells." (PMID 31478829, 2019). "Over-expression of (E) ESRP1, (F) ESRP2, or (G) both ESRP1 and ESRP2 in PC3 cells significantly slowed the growth of prostate cancer xenografts in vivo." (PMID 31478829, 2019).
prostate carcinoma (continued). "In this model, the AR controls expression of the master splicing regulator protein ESRP2, which then regulates the splicing patterns of key genes important for prostate cancer biology." (PMID 31478829, 2019). "(B) Real-time PCR analysis of ESRP1 and ESRP2 mRNA from normal and matched prostate cancer tissue from nine patients obtained from radical prostatectomy." (PMID 31478829, 2019). "This means that immunohistochemical analyses linking ESRP1 and ESRP2 expression with more aggressive disease progression might also be useful as prostate cancer biomarkers to apply in parallel to Gleason grading." (PMID 37752235, 2023). "Furthermore, ESRP2 expression can be directly induced within prostate cancer cell lines by exposure to androgens." (PMID 37752235, 2023). "Future work will be needed to more precisely identify the genes controlled by ESRP1 and ESRP2 that are important in aggressive prostate cancer, how they result in tumour growth, and how expression of these genes are modulated in response to ADT and during tumour metastasis." (PMID 37752235, 2023). "Hence expression changes in ESRP1 and ESRP2 in clinical prostate cancer disease progression, and downstream modulation of mRNA splicing patterns, most likely occur within the broader context of global changes taking place in the splicing environment." (PMID 37752235, 2023). "Mechanistically, we found that epithelial splicing regulator proteins (ESRP1 and ESRP2) are the splicing factor through which AR may regulate splicing of pre-mRNA in prostate cancer cells." (PMID 32820253, 2020). "Four different multivariate analyses were applied to evaluate whether ESRP1 or ESRP2 expression as well as our ESRP1/ESRP2 score is a statistically independent prognostic marker in all prostate cancers and the subset of ERG-negative and ERG-positive cancers." (PMID 33339518, 2020). "ESRP2 expression decreased following ADT in 7/7 prostate cancer patients." (PMID 31478829, 2019). "ESRP2 expression in clinical prostate cancer is repressed by ADT, which may thus inadvertently dampen epithelial splice programmes." (PMID 31478829, 2019). "Identifying the genes controlled by ESRP2 may reveal new drug targets to improve prostate cancer treatment." (PMID 31478829, 2019). "To enable us to test whether androgens may control splicing indirectly via transcriptional regulation of ESRP2, we next set out to identify a panel of endogenous ESRP2-responsive exons within prostate cancer cells." (PMID 31478829, 2019). "In prostate cancer cells in mice, extra ESRP2 slowed tumour growth." (PMID 31478829, 2019). "Since ESRP2 expression was repressed by ADT in patient prostate cancer tissue, we next investigated whether AR inactivation may influence mRNA splice isoforms that correlate with cancer progression." (PMID 31478829, 2019). "ESRP2 is a direct target for AR regulation in prostate cancer cells." (PMID 31478829, 2019). "We next monitored ESRP1 and ESRP2 expression profiles from prostate cancer patients." (PMID 31478829, 2019). "Our data identify an AR-ESRP2 axis controlling splicing patterns in prostate cancer cells, and further suggest that reduced ESRP2 levels in response to ADT may inadvertently help prime prostate cancer cells to facilitate longer term disease progression." (PMID 31478829, 2019). "Amongst the genes containing ESRP2-repressed exons that were also skipped in response to androgen stimulation were DOCK7 (exon 23), which encodes a guanine nucleotide exchange factor involved in cell migration; and RPS24 (exon 5), a gene that is highly expressed in prostate cancer." (PMID 31478829, 2019). "Thus, upregulation of ESRP1/ESRP2 gene expression in aggressive tumours, by either gene amplification or in response to androgens could be different means to the same end, and drive the progression of aggressive prostate cancer in a similar way." (PMID 37752235, 2023).
prostate carcinoma (continued). "Treatment of cultured prostate cancer cells with Casodex and enzalutamide model the molecular changes that occur during ADT, and has established a clear link between ESRP1/ESRP2 and androgens." (PMID 37752235, 2023). "Our data show a striking link between nuclear ESRP expression and adverse features in prostate cancer and identifies expression of ESRP1 and/or ESRP2 as independent prognostic markers with a potential for routine application." (PMID 33339518, 2020). "In prostate cancer, a meta-analysis reported significant up-regulation of ESRP1 and ESRP2 mRNAs in 719 prostate cancers from 11 previous studies including normal and malignant prostate tissues." (PMID 33339518, 2020). "In prostate cancers, nuclear ESRP1 and ESRP2 staining was more common and also more intense." (PMID 33339518, 2020). "(A) Analysis of RNAseq data from human prostate cancer pre- and post- androgen deprivation therapy (ADT) shows that there is a significant downregulation of ESRP1 and ESRP2 mRNA following ADT in all seven patients tested (p=6e-04, Mann Whitney U test)." (PMID 31478829, 2019). "Further analyses supported androgen-mediated control of ESRP2 but not ESRP1 in prostate cancer cell lines." (PMID 31478829, 2019). "This implies that ESRP1 and ESRP2 may have different biological functions and are regulated differently in some instances, as recently reported in prostate cancer, where ESRP2 but not ESRP1 is regulated by androgens." (PMID 34520622, 2022). "Other prostate cancer studies on ESRP1 or ESRP2 IHC expression are so far lacking." (PMID 33339518, 2020). "Consistent with Casodex preventing expression of some potentially harmful isoforms in prostate cancer cells, the splicing inclusion of NUMB exon three and TUFT1 exon two were reduced by Casodex (both these exons are normally activated by androgen exposure and ESRP2)." (PMID 31478829, 2019). "Ectopic expression of ESRP1 and ESRP2 protein expression in AR negative PC3 and DU145 cell line models reduced prostate cancer cell growth in vitro." (PMID 31478829, 2019). "Western blots detected high endogenous levels of both ESRP1 and ESRP2 proteins within the AR positive LNCaP and CWR22 RV1 prostate cancer cell lines, as compared to the AR negative PC3 and DU145 prostate cancer cell lines." (PMID 31478829, 2019).
clear cell renal cell carcinoma (5 papers, 2017 to 2023). "Interestingly, examination of TCGA data showed DNA methylation changes in ESRP2 in several adult cancers, including hypermethylation in two adult kidney cancers (renal clear cell carcinoma and renal papillary cell carcinoma)." (PMID 34520622, 2022). "Indeed, recent clinical and preclinical data have shown a tumor-suppressive effect of ESRP2 in clear cell renal cell carcinoma." (PMID 30049844, 2018).
bladder cancer (3 papers, 2024 to 2026). "In bladder cancer, a high level of ESRP2 expression has been linked to lung metastasis (p < 0.0001)." (PMID 38893126, 2024). "Moreover, another study showed that a reduction in ESRP1 or ESRP2 promoted bladder cancer cell growth and lung metastasis by altering FGFR2 splicing and macrophage polarization." (PMID 39132499, 2024).
colorectal cancer (3 papers, 2017 to 2020). A primary or metastatic malignant neoplasm that affects the colon or rectum. "In the present study, we show for the first time that the proto-oncogene MYC can regulate the promoter activation and splicing of the ITGA6 integrin gene through ESRP2 to favor the production of the pro-proliferative ITGA6A variant in colorectal cancer cells." (PMID 29401653, 2018). "Increased nuclear ESRP1 and ESRP2 staining in comparison to normal tissues was also found in several other tumor entities, including pancreatic ductal adenocarcinomas, oral squamous cell carcinomas, ovarian carcinomas, and colorectal carcinomas." (PMID 33339518, 2020). "Chromatin immunoprecipitation revealed that the proximal promoter sequences of ITGA6 and ESRP2 were occupied by MYC and actively transcribed in colorectal cancer cells." (PMID 29401653, 2018).
laryngeal carcinoma (3 papers, 2022 to 2024). Carcinoma that arises from the laryngeal epithelium. "The following year, another study found that MYCT1 significantly decreases the expression of miR-629-3p but increased the expression of ESRP2 in laryngeal cancer cells." (PMID 35803984, 2022). "Moreover, MYCT1 has also been reported to inhibit EMT and the migration of laryngeal cancer cells via the SP1/miR-629-3p/ESRP2 pathway." (PMID 37587470, 2023). "Additionally, a laryngeal cancer research study has reported a negative correlation between ESRP2 expression and lymphatic metastasis." (PMID 38893126, 2024).
lung carcinoma (3 papers, 2017 to 2022). "ESRP1 expression is linked to poor survival and metastasis in lung cancer, and both ESRP1 and ESRP2 are upregulated in oral squamous cell carcinoma relative to normal epithelium." (PMID 31478829, 2019).
ovarian carcinoma (3 papers, 2020 to 2025). A malignant neoplasm originating from the surface ovarian epithelium. "Overexpression of ESRP1 and/or ESRP2 has been described in various malignant tumors, such as pancreatic ductal adenocarcinoma, oral squamous carcinoma, ovarian cancer, and luminal-type breast cancer." (PMID 33339518, 2020).